INS (insulin)
Diseases named in the same sentence as INS in open-access papers (continued):
Sharing a sentence is not in itself a finding about the gene and the disease.
Insulin resistance (continued). "Metabolic derangement and excessive insulin resistance without sufficient compensation by increased insulin secretion in GDM predisposes the mother and offspring to both pregnancy complications and future risks of developing metabolic disorders and obesity." (PMID 37650554, 2023). "Treatment with C. odorata and coumarin offered an anti-hypertensive effect and caused modulation in insulin resistance, possibly through its effect on amended oxidative stress biomarkers (SOD, CAT, and MDA), inflammatory mediators (TNF-α and IL-6) and improved insulin sensitivity." (PMID 37033655, 2023). "In this regard, insulin plays a vital role in modulating lipogenesis, promoting glucose uptake and regulating triglyceride catabolism through the inhibition of hormone-sensitive lipase and contributing to insulin resistance." (PMID 37367840, 2023). "Similarly, HOMA-IR indicated the ND group is the only group that showed insulin sensitivity, and treating mice with O. aristatus (400 mg/kg) recovered the insulin resistance condition that was shown in the HFD group." (PMID 36678606, 2023). "However, empagliflozin has pleiotropic effects, such as reducing insulin levels, insulin resistance, glucotoxicity and lipotoxicity, and increasing glucagon secretion and ketone bodies production." (PMID 37152929, 2023). "We proposed that by focusing on sphingolipid metabolism, which plays a critical role in insulin signaling and the development of insulin resistance, CBG may provide a novel therapeutic approach for metabolic disorders, particularly insulin resistance." (PMID 37892425, 2023). "CXCL5 could induce insulin resistance by inhibiting the insulin signaling pathway in muscle, adipose tissue, and macrophages." (PMID 37420254, 2023). "HFD induced physiological insulin resistance and decreased acute hepatic insulin signalling to Akt." (PMID 36894641, 2023). "In insulin-resistant individuals, lipid oversupply from high-fat, high-calorie meals or excessive adipose lipolysis can contribute to enhanced fatty acid oxidation and worsening insulin resistance." (PMID 37175603, 2023). "Given the role played by insulin resistance and hyperglycemia in morbidity and mortality, interventions showing potential in enhancing insulin action in the peripheral tissue present opportunities to combat a range of pathologies associated with metabolic syndrome." (PMID 38203217, 2023). "Chromium supplementation may lower fasting insulin levels and insulin resistance in patients with PCOS." (PMID 38025704, 2023). "Specifically, evidence from animal studies has shown that excess production of glutathione peroxidase 1, which is the most common type of selenoprotein, may disrupt the insulin signalling pathway and lead to insulin resistance." (PMID 37299509, 2023). "It is well known that the excess adipose tissue may result in insulin resistance, while the excess muscle also affected the sensitivity of insulin." (PMID 37275645, 2023). "Although baseline characteristics were well balanced between the two treatment groups, residual confounders such as insulin levels and markers of insulin resistance may have an impact on our results." (PMID 36968629, 2023). "Thiazolidine is an insulin sensitizer and could reduce blood glucose by increasing peripheral tissue sensitivity to insulin and improving insulin resistance." (PMID 37868953, 2023). "Moreover, obese individuals had high levels of fasting blood insulin, which demonstrate insulin resistance in this group." (PMID 37319295, 2023). "Furthermore, AT improves insulin sensitivity by reducing inflammatory cytokines and oxidative stress responses, thus ameliorating the pathophysiologic pathways of insulin resistance." (PMID 37689713, 2023).
Insulin resistance (continued). "Positive effects were observed after the supplementation of Bifidobacterium pseudocatenulatum CECT7765 in mice for 7 weeks, such as reduction of the adipose tissue and improvements in insulin resistance, hepatic steatosis, and plasma levels of insulin, leptin, and IL-6." (PMID 37296485, 2023). "Brain insulin resistance is when brain cells fail to respond to insulin." (PMID 36902167, 2023). "Earlier initiation of interventions results in a greater duration of intervention exposure prior to GDM diagnosis, with the benefit of preconception commencement providing an opportunity to optimize insulin sensitivity prior to the onset of pregnancy-induced insulin resistance." (PMID 37794119, 2023). "Subjects were divided into groups with hyperinsulinemia (17 men and 24 women) and normal insulin levels (214 men and 205 women), who were also divided into the insulin resistance group (HOMA-IR > 2.7; 80 men and 105 women) and those without insulin resistance (151 men and 124 women)." (PMID 37510094, 2023). "Alongside rectifying hepatic glucose metabolism, taurine or carnosine could enhance hepatic insulin signaling to improve glucose tolerance and compensate for insulin resistance." (PMID 37571314, 2023). "Interestingly, in a number of complex syndromes, MPD occurs in combination with insulin resistance status, which is a complex pathological state of impaired cellular response to insulin in target cells such as adipocytes." (PMID 36627765, 2023). "However, maternal insulin sensitivity declines progressively in the second trimester, resulting in overt insulin resistance in the third trimester of pregnancy." (PMID 38229396, 2023). "In addition, DIO mice had a blunted response to insulin, indicating insulin resistance as assessed by ITT, in which the parameter AUCDIO in DIO mice was 52% higher than that of normal mice in the same batch (Con)." (PMID 36678603, 2023). "A better understanding of these mechanisms in humans will allow us to understand which functional step fails in response to insulin resistance and consequent increased insulin demand, and at which stage this progression towards beta cell dedifferentiation is reversible." (PMID 36280617, 2023). "Insulin resistance is an altered physiologic response to insulin stimulation of the target tissues, such as the liver, muscle, and adipose tissue, and the resistance hinders glucose metabolism, resulting in hypertrophy of beta cells, increased beta-cell insulin production, and hyperinsulinemia." (PMID 37175603, 2023). "The body attempts to compensate for this insulin resistance by augmenting insulin secretion." (PMID 37761031, 2023). "We interpret these findings to suggest that β‐catenin dysfunction may, in part, be involved in the development of skeletal insulin resistance and act by impairing insulin‐mediated actin‐cytoskeleton remodeling." (PMID 36807886, 2023). "Insulin resistance and / or insufficient insulin secretion are its pathogenesis." (PMID 37255814, 2023). "Skeletal muscle insulin resistance impairs this insulin-mediated glucose uptake and thereby increases the glycemic effect of foods which for sugars depends partially on intestinal digestion speed and resulting monosaccharide uptake, and partially on how fast glucose is cleared from the circulation." (PMID 37049441, 2023). "In this respect, the disrupted insulin signaling due to central insulin resistance in MetS might lead to neuroinflammation, vasculopathy, and ultimately the death of RGCs, thereby increasing the risk of glaucoma." (PMID 37620923, 2023). "Despite emerging evidence supporting the predictive capability of increased BCAAs levels in T2DM, researchers still contemplate whether BCAAs are true causative factors in insulin resistance and T2DM or merely passive biomarkers of impaired insulin action." (PMID 37755297, 2023).
Insulin resistance (continued). "As future studies further unravel the regulatory layers connecting these acute epigenetic changes to chronic epigenetic alterations in response to insulin resistance, we will gain critical insight into how these mechanisms relate to increased or decreased nutrient intake and insulin dysregulation." (PMID 37066881, 2023). "Based on these findings, it could be concluded that congenital autophagy inhibition impairs adipogenesis and leads to insulin sensitivity, whereas selective inhibition of this pathway in mature adipocytes results in insulin resistance." (PMID 37876013, 2023). "In addition to the challenges and costs associated with using injectable insulin, there is evidence indicating that intensive insulin use can lead to the development of insulin resistance in individuals with T1DM." (PMID 38020198, 2023). "Insulin resistance may increase serum insulin levels in T2DM and, by blocking IGF-binding proteins, indirectly increase IGF-1 biological activity." (PMID 36890832, 2023). "Certain viruses can interfere with insulin signaling pathways, inducing insulin resistance." (PMID 38239343, 2023). "Loss-of-function SNPs in the introns of the CDKAL1 gene were found to be associated with defects in insulin secretion but not with obesity or insulin resistance." (PMID 36902173, 2023). "The following measures were obtained at baseline and postintervention (9 months): demographics via survey; measured height, weight, and body mass index parameters; and glucose, insulin, homeostatic model assessment of insulin resistance, and a lipid panel via an optional fasting blood draw." (PMID 36626172, 2023). "Further support for a protective effect of estrogen on insulin sensitivity is an observed estrogen-mediated increase in insulin sensitivity in males, whereas a complete lack of estrogen synthesis or activity in men is associated with insulin resistance." (PMID 36678314, 2023). "The rs266729 variant of the adiponectin gene was associated with a significant increase in adiponectin levels and a decrease in the low-density lipoprotein, cholesterol and insulin levels, as well as a homeostasis model assessment for insulin resistance after implementing a calorie-restricted diet." (PMID 37298551, 2023). "Taken together, lipolytically cleaved soluble Gpc4, the release of which into human serum is fostered by elevated insulin levels in response to insulin resistance and obesity, seems to operate as an insulin-sensitizing adipokine and to counteract impaired insulin signaling via a feedback loop." (PMID 37238725, 2023). "Moreover, an increase in age can lead to insulin resistance, insulin secretion and insulin receptor abnormalities." (PMID 37076792, 2023). "DPP4 can also impair the insulin signaling pathway, thereby contributing to insulin resistance." (PMID 37525169, 2023). "Also, serum OCN in some investigations is inversely correlated with the homeostasis pattern of insulin resistance index, fasting plasma glucose, and fasting insulin." (PMID 36846642, 2023). "Consequently, overexpression of inflammatory molecules that result in the removal of IRS-1/2 receptors impede the insulin signaling pathway and lead to insulin resistance." (PMID 38140341, 2023). "Adiponectin treatment reverses high-fat-diet-induced insulin resistance through the increase in insulin-stimulated glucose in adipose tissue and muscles in mice; however, adiponectin agonists have not been well characterized and their availability for therapeutic purposes in humans is still limited." (PMID 38003291, 2023). "Because apelin appears to correct insulin sensitivity in conditions of severe insulin insensitivity, it may assist in the attenuation of burn-induced insulin resistance." (PMID 36779088, 2023). "Consistent with our hypothesis, mtSMPD5 was sufficient to promote insulin resistance in response to submaximal and maximal insulin doses." (PMID 38149844, 2023).
Insulin resistance (continued). "Insulin resistance (IR) is a physiological state in which insulin sensitivity decreases in target organs such as skeletal muscle, liver, and white adipose tissue, reducing glucose uptake and utilization, resulting in increased compensatory insulin secretion." (PMID 38007572, 2023). "Insulin resistance (IR) is defined as an increase in the production and secretion of insulin in the beta cells of the pancreas as a compensatory process for the alteration in the elimination of glucose in the target tissues—mainly the liver, muscles, and adipose tissue." (PMID 37628382, 2023). "This idea was driven by the hypothesis that a decline in insulin sensitivity is driven by insulin resistance (IR)." (PMID 37446104, 2023). "Despite the potential for improving skeletal muscle health, these changes are involved in insulin resistance and the deterioration of skeletal muscle performance, which depends on chronic exposure to endogen insulin or exogen analogs and occurs in a dose-dependent manner." (PMID 38201893, 2023). "Additionally, in vitro, in 3T3-L1 adipocytes, insulin-induced insulin resistance significantly decreased VLDL-R mRNA expression." (PMID 37762244, 2023). "As insulin resistance increases, beta cells try to compensate by increasing insulin output." (PMID 38283440, 2023). "Insulin resistance and insulin secretion decline are the core features of T2DM." (PMID 37484968, 2023). "As in muscle, hybrid IR/IGF-1R receptors are formed, and their abundance is increased in “wild-type” T2DM; of note, it is proposed that hybrid receptors could contribute to insulin resistance by binding IGF-1 with higher affinity than insulin." (PMID 36882643, 2023). "Studies propose that rosiglitazone may enhance insulin sensitivity, improving glucose utilization and potentially mitigating insulin resistance, a critical factor in DKA development." (PMID 38186506, 2023). "Based on our current results, we hypothesize that hypothalamic insulin resistance in the luteal phase may be responsible for cycle-dependent differences in brain-derived modulation of peripheral insulin sensitivity." (PMID 37735274, 2023). "In hepatocytes, PKD3, the dominant PKD isoform, suppresses insulin signaling and provides negative feedback for cholesterol and triglyceride synthesis, and its overexpression causes insulin resistance." (PMID 36672148, 2023). "This suggests that such mechanism could be present in other insulin-responsive cells and insulin resistance could have a broader physiological and evolutionary role." (PMID 37026009, 2023). "These discrepant findings may be due to the variable representation of women with different GDM phenotypes, i.e. with a varied contribution of insulin resistance, impaired postprandial insulin secretion and/or incretin resistance." (PMID 36717953, 2023). "It is hypothesized that higher insulin levels in the serum of obese individuals, resulting from increased insulin resistance, lead to increased renal excretion of Mg." (PMID 37446123, 2023). "There is interest in the impact that dietary interventions can have on preventing the transition from insulin resistance to type 2 diabetes, including a suggestion that the bioactive components of cocoa may enhance fasting insulin sensitivity." (PMID 36771271, 2023). "Preoperative carbohydrate (CHO) drinks may reduce the adverse effects of overnight fasting by minimizing postoperative insulin resistance, hyperglycemia, and the need for insulin treatment while maintaining skeletal and cardiac muscle function." (PMID 38098008, 2023). "Moreover, aldosterone impairs glucose-stimulated insulin secretion and insulin sensitivity in skeletal muscle and adipocytes, which contributes to insulin resistance in humans." (PMID 36950676, 2023). "This prompted us to investigate whether the microtubule polymerization was itself insulin responsive and/or affected by insulin resistance." (PMID 37073948, 2023).
Insulin resistance (continued). "It reduces circulating insulin levels and insulin resistance." (PMID 38137870, 2023). "Second, insulin users might harbor features that necessitate insulin use, including a greater degree of insulin resistance than oGLD users." (PMID 37196125, 2023). "Protein phosphorylation is central to the adipocyte insulin response, but how adipocyte signaling networks are dysregulated upon insulin resistance is unknown." (PMID 36808134, 2023). "This could indicate that evaluating BVRA may be valuable in understanding the molecular processes involved in insulin signaling activation and the development of insulin resistance." (PMID 37108445, 2023). "Insulin resistance was decreased, and insulin sensitivity was increased in groups fed RM." (PMID 37608169, 2023). "In addition, these protocols have been shown to lower fasting insulin and insulin resistance in adults with obesity." (PMID 37139450, 2023). "Supplementation of dietary BCAAs could moderately weaken the insulin sensitivity and metabolic efficiency of the mice but cannot induce insulin resistance." (PMID 36982473, 2023). "Adiponectin increases insulin sensitivity, lowers the level of circulating lipids and protects against atherosclerosis, and low levels of it are found in people with obesity, insulin resistance and type II diabetes." (PMID 37858203, 2023). "Thus, supplementation of curcumin in PCOS patients is beneficial in numerous ways, both in decreasing insulin resistance and improving insulin and glucose levels as well as exerting a protective effect against the hyperandrogenic effects in PCOS." (PMID 37569074, 2023). "The greater benefit of metformin in women with increased insulin resistance is in line with the known mechanisms of metformin, which is to reduce glucose production in the liver, improve peripheral glucose uptake and increase insulin sensitivity." (PMID 37794119, 2023). "Most individuals adapt to insulin resistance by an appropriate increase in insulin secretion." (PMID 36814640, 2023). "In addition, in subjects with normal plasma glucose concentrations, it has been found that hyperinsulinemia per se induced insulin resistance by insulin-induced downregulation of insulin receptor signaling." (PMID 36901984, 2023). "Insulin resistance (IR), an impaired response of peripheral tissues to insulin, is characterized by hyperinsulinemia, hyperglycemia, hypertension, dyslipidemia, visceral adiposity, hyperuricemia, elevated inflammatory markers, endothelial dysfunction and a prothrombic state." (PMID 37447192, 2023). "It is well established that individuals with insulin resistance tend to have higher insulin levels." (PMID 38137858, 2023). "It has been suggested that GM3, the simplest structure among gangliosides, is involved in insulin resistance, whereas it remains unclear whether insulin signaling diminished by GM3 actually aggravates the pathological conditions in metabolic disorders." (PMID 36827398, 2023). "This suggests that increased FA intake may impair the ability of older pregnant women to secrete adequate insulin to counteract the natural progression of insulin resistance in pregnancy." (PMID 37049394, 2023). "Insulin resistance (IR), in general, occurs when tissues show reduced sensitivity to insulin despite a normal or even decreased concentration in the blood, and the consequences can be impaired glucose uptake by the tissues, increased efficiency of gluconeogenesis and increased lipolysis." (PMID 37628596, 2023). "Upon high-fat condition, deletion of Sirt2 reduces muscle insulin sensitivity and contributes to liver insulin resistance in mice, potentially by affecting mitochondrial acetylation state, although opposite data were previously reported in vitro in muscle cells." (PMID 36901738, 2023). "In vitro and in vivo models suggest that aminoadipic acid may increase insulin secretion as a compensatory mechanism to maintain glucose homeostasis in early insulin resistance." (PMID 37110200, 2023).